SUN2 (Sad1 and UNC84 domain containing 2)
Diseases named in the same sentence as SUN2 in open-access papers (continued):
Sharing a sentence is not in itself a finding about the gene and the disease.
lung carcinoma (7 papers, 2015 to 2025). "Low SUN2 expression was shown to be associated with poor outcomes in patients with lung cancer, indicating that the loss of SUN2 is likely to present prognostic value." (PMID 26658802, 2015). "To investigate the mechanism underlying the reduction of SUN2 levels in lung cancer cells, we analyzed the promoter sequence of SUN2 and found a CpG island in this region." (PMID 26658802, 2015). "To explore the mechanism underlying the decrease in SUN2 expression in lung cancer cells, we first examined the methylation status of the SUN2 promoter, given that hypermethylation of the promoters of many tumor suppressor genes leads to a decrease in their expression in cancer." (PMID 26658802, 2015). "Overexpression of SUN2 increases apoptosis, whereas knockdown of SUN2 reduces it in naïve and cisplatin-treated lung cancer cells." (PMID 32351716, 2020). "The overexpression of SUN2 increased the apoptosis rate in lung cancer cells compared with the control cells." (PMID 26658802, 2015). "In this report, we showed that SUN2 decreases glucose uptake, the glycolytic rate and lactate production in lung cancer cells by decreasing the expression of GLUT1 and LDHA." (PMID 26658802, 2015). "Overexpression of SUN2 inhibits cell proliferation, colony formation and migration in lung cancer, whereas knockdown of SUN2 promotes cell proliferation and migration." (PMID 26658802, 2015). "In this report, we demonstrated for the first time that SUN2 is a key player in lung cancer progression by inhibiting the Warburg effect." (PMID 26658802, 2015). "Taken together, these findings indicated that SUN2 inhibits lung cancer cell proliferation and migration." (PMID 26658802, 2015). "Based on the expression level of SUN2 in these lung cancer cells, we constructed stable cell lines with either ectopic expression of SUN2, in H460 cells, or silenced SUN2, in H1975 cells." (PMID 26658802, 2015). "Our results demonstrated that SUN2 suppresses cell proliferation and migration, promotes apoptosis and enhances chemotherapy sensitivity to cisplatin in lung cancer." (PMID 26658802, 2015). "We demonstrated that the mRNA and protein levels of SUN2 were significantly decreased in lung cancer by performing data mining and immunohistochemistry analysis." (PMID 26658802, 2015). "SUN2 is significantly down-regulated in lung cancer tissues compared with the paired normal tissues (P < 0.01)." (PMID 26658802, 2015). "We also show that the down-regulation of SUN2 is at least partly mediated by class III of the sirtuin family member SIRT5 in lung cancer." (PMID 26658802, 2015). "We found that SUN2 expression was decreased in lung cancer tissue compared with paired normal tissues and that higher SUN2 levels predicted better overall survival and first progression survival." (PMID 26658802, 2015). "We also reported that SIRT5 is at least partly responsible for the down-regulation of SUN2 in lung cancer cells." (PMID 26658802, 2015). "First, we detected the expression of SUN2 in lung cancer cell lines using quantitative real-time PCR and western blotting." (PMID 26658802, 2015). "Higher SUN2 level predicts a better overall survival in lung cancers." (PMID 35372566, 2022). "Moreover, SUN2 was found to enhance the chemotherapy sensitivity in lung cancer cells exposed to cisplatin." (PMID 35372566, 2022). "Moreover, SIRT5 was determined to have a partial inhibitory effect on the tumor suppressor SUN2, which was found to increase the sensitivity of lung cancer to cisplatin by inducing apoptosis." (PMID 31456942, 2019). "Given that SUN2 expression is down-regulated in lung cancer, we next asked whether it is involved in regulating the biological behaviors of lung cancer cells." (PMID 26658802, 2015). "However, the role of SUN2 in lung cancer remains uncharacterized, and the mechanism by which SUN2 regulates cancer cell biological characteristics also needs to be addressed." (PMID 26658802, 2015).
lung carcinoma (continued). "Because SUN2 inhibits lung cancer cell proliferation, we next investigated whether SUN2 affects the apoptosis of lung cancer cells." (PMID 26658802, 2015). "In summary, our findings demonstrate that SUN2 plays a tumor suppressor role by repressing the Warburg effect and could serve as a clinical predictor in lung cancer." (PMID 26658802, 2015). "This novel SIRT5/SUN2 axis may be valuable for developing new strategies for treating patients with lung cancer." (PMID 26658802, 2015). "Interestingly, according to the Protein Atlas database, the protein expression level of SUN2 is decreased in 75% (9 out of 12) of lung cancer tissues." (PMID 26658802, 2015). "This novel SIRT5/SUN2 axis may be useful for the development of new strategies for treating patients with lung cancer." (PMID 26658802, 2015). "Additionally, SUN2 increases the sensitivity of lung cancer to cisplatin by inducing cell apoptosis." (PMID 26658802, 2015). "However, SIRT5 was found to downregulate the expression of SUN2 in lung cancer." (PMID 39979670, 2025). "We then examined whether SUN2 inhibited the migration of lung cancer cells." (PMID 26658802, 2015). "In this study, we provide the first evidence that SUN2 plays a tumor suppressor role by suppressing the expression of GLUT1 and LDHA to inhibit the Warburg effect in lung cancer." (PMID 26658802, 2015). "Our results revealed that SUN2, another component of the LINC complex, plays an important role in inhibiting cell proliferation and migration in lung cancer." (PMID 26658802, 2015). "SAD1/UNC84 domain protein-2 (SUN2) is a member of the nuclear membrane LINC (nuclear skeleton-cytoskeletal junction) complex, which inhibits the proliferation and migration of cancer cells and increases the sensitivity of lung cancer cells to cisplatin." (PMID 39979670, 2025). "To address the issue of whether SUN2 regulates the Warburg effect, we investigated the effect of SUN2 on GLUT1 and LDHA expression in lung cancer cells." (PMID 26658802, 2015). "SUN2, a key component of LINC (linker of nucleoskeleton and cytoskeleton) complex located at the inner nuclear membrane, plays unknown role in lung cancer." (PMID 26658802, 2015).
cardiomyopathy (5 papers, 2014 to 2024). A disease of the heart muscle or myocardium proper. "The integral nature of SUN proteins in the LINC complex makes it surprising that compared to other LINC components, relatively few mutations in SUN1 and SUN2 are associated with cardiomyopathy." (PMID 29869195, 2018). "Furthermore, armed with the knowledge that SUN proteins likely play key roles as genetic modifiers, it would be interesting to sequence SUN1 and SUN2 genes in patients with cardiomyopathy in which other LINC complex mutations have been identified that may not fully explain the resulting phenotype." (PMID 29869195, 2018). "Our genetic results suggest that mutations or polymorphisms in SUN1 and SUN2 may cause muscular dystrophy and act as modifiers of EDMD and cardiomyopathy." (PMID 25210889, 2014).
Emery-Dreifuss muscular dystrophy (4 papers, 2012 to 2022). Emery-Dreifuss muscular dystrophy (EDMD) is characterized by muscular weakness and atrophy, with early joint contractures and cardiomyopathy. "While specific SUN1 and SUN2 alleles have been directly connected to Emery-Dreifuss muscular dystrophy (EDMD) and related myopathies, SUN proteins may also have indirect effects in disorders in which the LMNA gene is mutated." (PMID 28747499, 2017).
Hepatic fibrosis (4 papers, 2018 to 2023). The presence of excessive fibrous connective tissue in the liver. "We next assessed potential molecular mechanisms underlying the low expression of SUN2 during hepatic fibrosis." (PMID 30282980, 2018). "Moreover, SUN2 is necessary for maintaining genomic stability, and DNA damage plays an important pathogenic role in liver fibrosis." (PMID 37056286, 2023). "Considering the evidence indicating SUN2 hypermethylation in hepatic fibrosis mice, we hypothesized that silencing of the SUN2 gene by DNA hypermethylation may be associated with HSCs activation and liver fibrogenesis." (PMID 30282980, 2018). "Our study provides initial evidence of SUN2 downregulation in HSCs from hepatic fibrosis mice compared with vehicle-treated mice." (PMID 30282980, 2018). "Functionally, significant effects of SUN2 overexpression by alleviation of liver injury and suppression of fibrosis were confirmed in hepatic fibrosis mice following AAV-SUN2-GFP administration." (PMID 30282980, 2018). "In conclusion, we revealed for the first time that a potential role of SUN2 in fibrotic diseases, particularly hepatic fibrosis." (PMID 30282980, 2018). "Taken together, these results revealed a remarkably lower expression level of SUN2 during liver fibrogenesis, and that AAV-mediated SUN2 overexpression suppressed liver injury and myofibroblast marker expression in hepatic fibrosis mice." (PMID 30282980, 2018). "Considering hypermethylation of SUN2 was found in hepatic fibrosis mice, we next investigated the potential functions and relevant mechanisms of SUN2 in hepatic fibrosis." (PMID 30282980, 2018). "Taken together, our study indicated regulation of SUN2 in HSCs activation and amelioration of the pathogenesis of hepatic fibrosis in mice." (PMID 30282980, 2018). "Lower SUN2 staining by immunohistochemistry was observed in hepatic fibrosis mice compared with vehicle-treated mice." (PMID 30282980, 2018). "Therefore, hypermethylation of the SUN2 gene mediates the decrease in SUN2 expression in liver fibrosis." (PMID 37056286, 2023). "SUN2 deficiency induces DNA damage and HSC activation, leading to liver fibrosis." (PMID 37056286, 2023). "Furthermore, as promising biomarkers of hepatic fibrosis, 33 CpG sites were hypermethylated in the SUN2 gene of DNA samples from hepatic fibrosis model mice compared with vehicle-treated mice." (PMID 30282980, 2018). "Notably, enhancing SUN2 expression exerted anti-fibrogenesis effects and attenuated HSCs activation, the principal contributor to hepatic fibrosis." (PMID 30282980, 2018). "Interestingly, the results revealed hypermethylation of SAD1/UNC84 domain protein-2 (SUN2) during hepatic fibrosis." (PMID 30282980, 2018). "In conclusion, these findings provide substantial new insights into SUN2 in hepatic fibrosis." (PMID 30282980, 2018). "Our future studies will assess the role of SUN2 in reversing progression of hepatic fibrosis." (PMID 30282980, 2018). "In addition, mRNA and protein expression of SUN2 was significantly downregulated in primary HSCs from hepatic fibrosis mice." (PMID 30282980, 2018). "Collectively, these results highlight SUN2 as an anti-fibrogenesis factor that may be a promising therapeutic biomarker for treatment of hepatic fibrosis." (PMID 30282980, 2018). "Notably, we found that SUN2 had aberrant hypermethylation in DNA samples from hepatic fibrosis mice compared with vehicle." (PMID 30282980, 2018). "Taken together, these results suggested that phosphorylation and activation of AKT may be one of responsible pathway for SUN2-regulated amelioration of hepatic fibrosis features." (PMID 30282980, 2018). "In this study, we investigated the functions and molecular mechanisms of SUN2 in hepatic fibrosis." (PMID 30282980, 2018). "Interestingly, we found SAD1/UNC84 domain protein-2 (SUN2) gene hypermethylation at CpG sites during liver fibrogenesis in mice with CCl4-induced hepatic fibrosis, which was accompanied by low expression of SUN2." (PMID 30282980, 2018).
Hepatic fibrosis (continued). "However, the roles of SUN2 in fibrotic diseases, specifically hepatic fibrosis, remain speculative." (PMID 30282980, 2018). "However, the functions and relevant mechanisms of SUN2 in hepatic fibrosis had not been investigated." (PMID 30282980, 2018).
progeria (4 papers, 2011 to 2023). "Therefore, elevated Sun2 can be a downstream consequence of abnormal nuclear shape caused by Zmpste24 loss in progeria cells." (PMID 37198162, 2023). "Our results reveal that Sun2 is greatly involved in mediating mechanical stress-induced nuclear damage by regulating nuclear mechanical properties, and Sun2 suppression can be a novel therapeutic target for treating progeria aging or aging-related diseases." (PMID 37198162, 2023). "Our recent study of Hutchinson-Gilford progeria syndrome (HGPS) disease revealed the role of nuclear membrane protein Sun2 in mediating nuclear damages and cellular senescence in progeria cells." (PMID 37198162, 2023). "Here we further verified that Sun2 is critical for mediating increased nuclear abnormalities and mechanical stress-induced nuclear damages in progeria cells, and the suppression of Sun2 expression is effective in reducing the nuclear abnormalities and damages." (PMID 37198162, 2023). "We observed that increased cytoskeletal stiffness and RhoA activation in progeria cells were directly coupled with increased nuclear blebbing, Sun2 expression, and micronuclei‐induced cGAS‐Sting activation, part of the innate immune response." (PMID 32710480, 2020). "Therefore, in addition to increased deposition of prelamin A, the elevated level of Sun2 can be another critical contributor to promote the increased nuclear abnormalities and DNA damages in progeria cells." (PMID 37198162, 2023). "Here we further examined whether Sun2 suppression in Z24−/− MSCs was able to rescue impaired nuclear deformability of progeria cells." (PMID 37198162, 2023). "While, the suppression of Sun2 expression in progeria cells may have reduced the strong coupling between cytoskeleton and nuclear lamina, which avoids or reduces the harmful impact of extreme mechanical stress on nucleus." (PMID 37198162, 2023). "RhoA activation in progeria cells could be a result of Sun2 activation as well as increased pro‐inflammatory signaling, pro‐fibrotic signaling, DNA damage, ROS production, and activated mechano‐sensing signaling." (PMID 32710480, 2020). "The increased activation of Sun2 in these in vitro cultured progeria cells is not caused by stiffer substrate/ECM, but rather is a result of an intrinsic change in the mechanical properties of the cell nucleus." (PMID 32710480, 2020). "However, suppression of Sun2 was effective in improving the survival of Z24−/− MSCs after migrating through the narrow matrix space of the transwell filter, indicating a potentially crucial role of Sun2 protein in regulating nuclear deformability in progeria cells." (PMID 37198162, 2023). "Therefore, the over-activated Sun2 expression in progeria cells may indicate a close and strong coupling between cytoskeleton and nuclear lamina, and thus the extreme mechanical stress was able to exert greater impact on nuclear architecture and characteristics." (PMID 37198162, 2023). "We believe that this beneficial effect of Sun1 reduction in progeria cells may be partially due to the regulation of mechanical features of nucleus or cytoskeleton since nuclear lamina network is connected to cytoskeleton by both Sun1 and Sun2 in the LINC complexes." (PMID 32710480, 2020). "Also, we observed that the expression level of Sun2, but not Sun1 or overall level of Lamin A/C, was significantly changed in progeria cells in contrast to WT cells." (PMID 37198162, 2023). "We have proposed the potential mechanisms of cytoskeletal stiffening in mediating nuclear blebbing, micronuclei formation, and cellular senescence, the involvement of the RhoA and Sun2 factors, and how increased ECM, nucleoskeletal, and cytoskeletal stiffness may be coupled in progeria cells." (PMID 32710480, 2020).
muscular dystrophy (3 papers, 2014 to 2022). Muscular dystrophy (MD) refers to a group of more than 30 genetic diseases characterized by progressive weakness and degeneration of the skeletal muscles that control movement. "In this study, we have demonstrated, in several different systems, that muscular dystrophy-associated mutations in SUN1 or SUN2 impair nuclear coupling to the both actin and microtubule networks and disrupt nuclear movement and positioning." (PMID 25210889, 2014).